LAP3 (leucine aminopeptidase 3)
Description:
Cytosolic metallopeptidase that catalyzes the removal of unsubstituted N-terminal hydrophobic amino acids from various peptides. The presence of Zn(2+) ions is essential for the peptidase activity, and the association with other cofactors can modulate the substrate spectificity of the enzyme. For instance, in the presence of Mn(2+), it displays a specific Cys-Gly hydrolyzing activity of Cys-Gly-S-conjugates. Involved in the metabolism of glutathione and in the degradation of glutathione S-conjugates, which may play a role in the control of the cell redox status.
Synonyms: LAPEP; PEPS; LAP; HEL-S-106
Tractability: Small molecule: a drug acting on it is in phase 2 or 3 trials; it belongs to a druggable protein family. PROTAC: ubiquitination databases record sites on it; its protein half-life has been measured; a small molecule that binds it is known.
Target class: Metallo protease; Enzyme; Metallo protease MF clan; Metallo protease M17 family; Protease
Gene: Protein-coding gene on chromosome 4 (17,577,198 to 17,607,975, forward strand). Ensembl gene ENSG00000002549.
Subcellular location: Cytoplasm
Subcellular location (Human Protein Atlas): Cytosol; Calyx; Mid piece; Principal piece
Gene Ontology:
Molecular function: protein binding; aminopeptidase activity; carboxypeptidase activity; metalloexopeptidase activity; manganese ion binding; metal ion binding; metalloaminopeptidase activity; peptidase activity
Biological process: proteolysis
Cellular component: extracellular exosome; focal adhesion; mitochondrion; nucleus; cytoplasm; trans-Golgi network
Genetic constraint (gnomAD): Loss-of-function variants: 29 observed, 40.64 expected, observed/expected ratio (o/e) 0.71, 90% interval 0.53 to 0.97. The upper end of that interval is the gene's LOEUF score, 0.97, which puts it in group 4 of 6, group 1 being the genes least tolerant of losing a copy. Missense variants: 516 observed, 559.97 expected, observed/expected ratio (o/e) 0.92, 90% interval 0.86 to 0.99. Synonymous variants: 222 observed, 201.89 expected, observed/expected ratio (o/e) 1.1, 90% interval 0.99 to 1.23.
Homologues: Orthologues: chimpanzee LAP3 (100% identical), macaque LAP3 (99% identical), dog LAP3 (92% identical), rabbit LAP3 (92% identical), guinea pig LAP3 (92% identical), rat Lap3 (91% identical), mouse Lap3 (90% identical), pig LAP3 (88% identical), tropical clawed frog lap3 (69% identical), zebrafish lap3 (68% identical), Drosophila melanogaster S-Lap1 (43% identical), Drosophila melanogaster S-Lap2 (42% identical), and 6 more. Paralogues in human: NPEPL1 (25% identical).